ACE (angiotensin I converting enzyme)
Diseases named in the same sentence as ACE in open-access papers (continued):
Sharing a sentence is not in itself a finding about the gene and the disease.
COVID-19 (continued). "The relationship between ACE inhibitor/AR blocker use and the incidence of severe COVID-19 has been conflicting and at present, where most authorities do not recommend discontinuing long-term ACE inhibitor/AR blocker treatments." (PMID 32670694, 2020). "Current evidence suggests that ACE inhibitors do not worsen outcomes in COVID-19 and should be continued in stable patients." (PMID 32629804, 2020). "Whether the use of ACE inhibitors and ARB affects the mortality of COVID-19 patients has been debated." (PMID 33195473, 2020). "The main objective is to describe the correlation between use of ACE inhibitors or ARBs and clinical outcome, defined by admission to the hospital, duration of stay, intensive care unit (ICU) admission and survival, in patients with confirmed COVID-19." (PMID 32587077, 2020). "Trials are needed to evaluate the use of ACE inhibitors and ARB’s in COVID-19 patients." (PMID 32369402, 2020). "Some authors also hypothesize that ACE inhibitors and Angiotensin Receptor Antagonist (ARB) can induce protection from COVID-19." (PMID 33022004, 2020). "Though the usefulness of ACE inhibitors or ARBs is uncertain and based on retrospective cohort studies, ARB was recently approved for clinical trials to evaluate its potential for the treatment of COVID-19 patients." (PMID 32585805, 2020). "Clinical trials are also ongoing to assess instead clinical benefits of continuing or not the treatment with ARBs or ACE inhibitors in patients with COVID-19 (NCT04330300, NCT04351581, NCT04353596, and NCT04329195)." (PMID 32850989, 2020). "Although there is currently no convincing evidence to suggest that ACE inhibitors or ARBs have a beneficial or harmful role in COVID-19, further studies are needed to resolve this question." (PMID 33059711, 2020). "SARS-CoV-2 uses ACE2 as its cellular receptor, resulting in ACE2 degradation and ACE/ACE2 imbalance, which could drive Ang II-mediated lung injury in COVID-19." (PMID 32887634, 2020). "This led to the hypothesis (hypothesis 1) that SARS-CoV-2-mediated downregulation of ACE2 disturbs the balance between ACE/AngII/AT1R and ACE2/Ang1–7/MasR signalling in the lungs and thereby contributes to the development of ARDS in COVID-19 patients." (PMID 32514935, 2020). "However, to date, there are no conclusive data demonstrating beneficial or adverse outcomes with background use of ACE-inhibitors, ARBs or other RAS antagonists among COVID-19 patients with a history of cardiovascular disease treated with these drugs." (PMID 32849666, 2020). "Reducing the oxidative stress secondary to the imbalance between ACE and ACE2 could be the best approach for the prevention and treatment of COVID-19." (PMID 32708578, 2020). "Different reports state that ACE inhibitors (ACEi) and Ang II receptor blockers (ARBs), both inducing the expression of ACE2, may be beneficial in COVID-19." (PMID 32930095, 2020). "Our findings show that there is no need to interrupt treatments for CVD in COVID-19 patients; in particular, the treatment with ACE inhibitors/ARBs should be continued in order to reduce potential cardiovascular derangement in COVID-19 patients." (PMID 33195473, 2020). "Dysregulation of the ACE/ACE2 axis by ADAM17 may further impact vascular tone and fluid homeostasis, contributing to complications such as pulmonary hypertension and organ damage in severe COVID-19." (PMID 40725601, 2025). "These ACE inhibitory peptides' dual activity set them apart from synthetic medications like lisinopril and captopril, which were not demonstrated to inhibit ACE2 activity and could be a therapy option for COVID-19." (PMID 38633607, 2024). "Also, the ACE-1 regulates the ACE-2 expression, so it is speculated to influence the COVID-19 severity." (PMID 37426824, 2023).
COVID-19 (continued). "This shift in the balance between ACE and ACE-2, in favor of ACE, can result in increased angiotensin II production and activation of the RAAS, leading to the release of proinflammatory cytokines and contributing to the development of cardiovascular and renal complications in COVID-19." (PMID 37048725, 2023). "Thus, the ACE and ANPEP genes may contribute to the severity and progression of COVID-19 by influencing the virus’s ability to enter human cells and modulating the response of the RAS to the infection." (PMID 38813031, 2023). "In the present study, acid-induced ALI could also contribute to the development of inflammation and disrupt the balance between ACE and ACE2, and then hACE2 TG and mACE2 KO mice were used to study the role of ACE2 in COVID-19-related ALI pathogenesis and the therapeutically applicable research." (PMID 37763673, 2023). "Moreover, ACE levels were higher in patients who were admitted to the ICU and died due to COVID-19." (PMID 37432962, 2023). "An area of ongoing interest, which was not rigorously investigated, is whether ACE inhibitors or angiotensin receptors blocker effect mortality in the COVID-19 population; however, recent randomized controlled trials have not shown a moratlity benefit." (PMID 36996126, 2023). "Results show that patients with cardiovascular disease using ACE inhibitors and ARB therapies are not at a higher risk of severe COVID-19 on their admission at the hospital, and maintaining the therapy during hospitalization is associated with a lower risk of death." (PMID 37189632, 2023). "The first-line drugs for hypertension treatment are ACE inhibitors (ACEi, -prils) and Angiotensin II Receptor Blockers (ARBs, -sartans), which are clearly established to increase ACE2 levels and could contribute to COVID-19 severity." (PMID 37762258, 2023). "The working hypothesis was that in COVID-19, tissue ACE2 is lowered, leading to unopposed ACE activity and high Ang II levels as well as impaired organ protection, and that signs of this activity are reflected in the serum protease activity and measurable using the neuropeptide reporter assay (NRA)." (PMID 35330406, 2022). "Another limitation worth mentioning is that we could not evaluate other genes involved in ACE and ACE2 pathways that could be contributing to the increased risk for severe COVID-19 outcome seen for the T allele of ACE2 rs228566 polymorphism." (PMID 35250987, 2022). "ACE-S was significantly lower with severe COVID-19 and did not correlate with ACE concentrations." (PMID 36418458, 2022). "Angiotensin I converting enzyme and angiotensin converting enzyme 2, coded by the genes ACE and ACE2, respectively, are critical regulators of this pathway and may also contribute to multiple organ injuries in COVID-19." (PMID 35795626, 2022). "In breakthrough COVID-19 infections, characterized by mild clinical course, we observed increased percentage of in-vitro NET-osis, higher CD4+ CD45RO+ and CD8+ CD45RO+ T cells healthy or mild-COVID-19 not-vaccinated patients, reduced by 24 h of treatment with ACE inhibitor ramipril." (PMID 35508575, 2022). "In other words, these blockers may represent potential neuroprotective drugs in COVID-19, but broader clinical studies such as those performed with ACE inhibitors for the treatment of hypertension in COVID-19 patients, are still lacking." (PMID 35966209, 2022). "Furthermore, the ACE2 polymorphism is associated with the varying degrees of disease severity and clinical outcomes of COVID-19, with the absence of ACE-DD genotype conferring protection against severe lung injury." (PMID 35371838, 2022). "Employing the molecular docking and systems network pharmacological strategies to uncover the molecular mechanisms, anti-SARS-CoV2/COVID-19 effects of these potential bioactive molecules could be shown to be altered by key bioactives and some corresponding genes such as MAPK14, ACE, TLR4, and MAPK8." (PMID 36144690, 2022).
COVID-19 (continued). "The variability in ACE expression lets the ACE2 not linked to the virus free to convert angiotensin II into angiotensin 1-7, thus reducing the chance of pulmonary edema occurring during COVID-19." (PMID 35897265, 2022). "While some authors were warning against the potential deleterious role of ACE2 and therefore of RAAS blockers, others have been claiming that restoring a disrupted ACE2-Ang1-7/ACE-Ang II homeostasis, for instance by using RAAS blockers, might actually be beneficial in COVID-19." (PMID 33692701, 2021). "Angiotensin II receptor 1 (AGTR1) may drive COVID-19 pathology: AGTR1 is G-protein coupled receptor (GPCR), mediates signaling and most functions of angiotensin-II that generated by the angiotensin-I converting enzyme (ACE1)." (PMID 34805533, 2021). "Based on these findings, the counterbalance between ACE and ACE2 activities in COVID-19 may play a crucial role in the thrombo-inflammatory processes described in severe pneumonia with evolution in ARDS, and the D/D genotype of ACE could also be a part of this crucial pathophysiological aspect." (PMID 34441050, 2021). "However, the disequilibrium between ACE and ACE2 activity, a pathophysiological feature of aging, is likely to play a key role in determining the disease severity in older people affected by COVID-19." (PMID 34945176, 2021). "In addition, most patients were more than 75 years old; thus, the absence of relation between ACE-2 expression and age should be confirmed in larger case series, including younger patients, even if severe forms of COVID-19 rarely occur at this age." (PMID 34073591, 2021). "Although the effects of such drugs as ACE inhibitors (ACEIs) and angiotensin-receptor blockers (ARB) on ACE2 in patients with COVID-19 remain unclear, previous findings led to increased concern that ACEIs and ARBs may increase (or decrease) mortality in patients with COVID-19." (PMID 34704822, 2021). "Moreover, they do not recommend initiating ACE inhibitors/ARBs in COVID-19 patients unless another clinical indication (like hypertension, diabetes)." (PMID 34345233, 2021). "As ACE2 is critical to SARS-CoV-2 infection, an imbalance in the RAS, with a shift towards ACE/Ang II and suppressing ACE2/Ang-, may be an important mediator of COVID-19 pathophysiology." (PMID 34178717, 2021). "ACE-1 also acts as an inactivator of BK, which makes it feasible that an inhibitor of ACE-1 might increase the levels of active BK and thereby aggravate the ARDS condition in COVID-19 patients." (PMID 33692801, 2021). "In our cohort, ACE, as well as aldosterone, were not increased in COVID-19 patients." (PMID 34945736, 2021). "However, when the renin, ACE-1, and angiotensin receptor inhibitors have been grouped together in studies, this link to COVID-19 severity has not been confirmed." (PMID 33692801, 2021). "This dual activity distinguishes these ACE inhibitory peptides from synthetic drugs, such as Captopril and Lisinopril which were not shown to inhibit ACE2 activity, and may represent a potential strategy in the treatment of COVID-19." (PMID 34769093, 2021). "There was a theoretical endorsement that the increase of ACE2 by the indirect effects of AngII receptor blockers (ARB) and ACE inhibitors taken by patients with CVD and related comorbidities, could enhance docking sites for SARS-CoV-2, leading to severe COVID-19." (PMID 33498183, 2021). "Another protein, ACE, is neither specific nor sensitive for the diagnosis of sarcoidosis, being elevated in several other non-sarcoid disorders, and its role as a biomarker for the diagnosis of COVID-19 has not been investigated so far." (PMID 33514012, 2021). "Finally, we suggest that a low ACE/ACE2 ratio and cell sorting according to the cell cycle phase, should be additionally considered among the minimum criteria for establishing stem cell-based products for the treatment of COVID-19." (PMID 34769218, 2021).
COVID-19 (continued). "In fact, although initial epidemiological studies showed that medication with ARBs or ACE inhibitors did not affect infectivity of SARS-CoV-2 and severity of COVID-19 in the patients, recent clinical studies have suggested that ARBs or ACE inhibitors provide a good prognosis to the patients." (PMID 34815389, 2021). "Moreover, empirical studies have not confirmed the connections between ARB and ACE-inhibitor use and COVID-19 diagnosis, hospital admission due to COVID-19, and COVID-19 severity." (PMID 34853605, 2021). "Whether ACE inhibitor and/or ARB use is clearly beneficial, neutral, or deleterious in the context of COVID-19-induced pneumonia remains to be seen, and this represents a significant gap in the literature that some have described as a possible “double-edged sword”." (PMID 32635289, 2020). "Based purely on experimental studies in which RAS pathway inhibitors were administered in vivo to humans/rodents, a reasonable hypothesis of using inhibitors that block both ACE and ACE2 zinc metalloproteases and their downstream pathways in COVID-19 patients will be proposed." (PMID 32708755, 2020). "Thus, monitoring ACE, tACE2, sACE2, ANG I, ANG II, ANG 1-7, and ANG 1-9 during COVID-19 may provide clues to develop effective treatments." (PMID 33519802, 2020). "Because of the virus infection depend on ACE2, pharmacological manipulation of the RAS through angiotensin converting enzyme (ACE) inhibitors, angiotensin receptor blockers (ARBs), and soluble recombinant ACE2 proteins administration have been discussed as a potential therapy for COVID-19." (PMID 33178033, 2020). "However, ACE, which counterbalances ACE2 in the RAS, is poorly understood in COVID-19." (PMID 33238910, 2020). "Moreover, some ACE inhibitors (ACEi) or angiotensin receptor blockers (ARB), which are used to treat comorbidities in COVID-19 patients, might increase the level of ACE2 in myocardial cells, theoretically, leading to elevated risk for cardiac injury." (PMID 32974109, 2020). "Furthermore, a recent study demonstrated that RAAS inhibitors (ACE inhibitors and angiotensin-receptor blockers) do not have negative impact on patients with COVID-19." (PMID 33118741, 2020). "Various theories about drugs such as ACE inhibitors or angiotensin II receptor blockers (ARBs) in relation to severe acute respiratory syndrome coronavirus 2 (SARS-CoV-2) and clinical outcomes of COVID-19 are circulating in both mainstream media and medical literature." (PMID 32587077, 2020). "Thus, ACE/Ang II/AT1R is upregulated, an essential characteristic for COVID-19 bad evolution." (PMID 33042994, 2020). "Since angiotensin-converting enzyme (ACE)-2 is a receptor for SARS-CoV-2, and ACE inhibitors and angiotensin receptor blockers are predicted to increase ACE-2 expression, it was initially feared that their use might exacerbate COVID-19." (PMID 33380345, 2020). "Since both ACE2 and ACE enzymes are activated by high concentrations of chloride and zinc ions, it is possible to hypothesise an activation of both arms of the RAS in ARDS induced by smoke bombs as well as in COVID-19 patients." (PMID 32708755, 2020). "In addition, the counterbalance between angiotensin-converting enzyme (ACE) and ACE2 activities occurring in COVID-19 may play a crucial role in the thrombo-inflammatory process." (PMID 33585520, 2020). "In this randomized open-label trial of losartan versus usual care, our primary hypothesis was that losartan compared to usual care decreases 28-day mortality and is safe in adults not previously on ARBs or angiotensin-converting enzyme (ACE) inhibitors who were hospitalized for acute COVID-19." (PMID 39325643, 2024). "However, issues with the method used to assess ACE activity in this study could have contributed to the observed results, similarly to the interference of the fluorescent ACE2 assay with human serum or serum albumin in COVID-19." (PMID 37986086, 2023).
COVID-19 (continued). "However, the ACE activity enzyme could be involved in the severity of COVID-19 and the outcome in post-COVID-19 patients, but this has not been previously evaluated." (PMID 37108839, 2023). "Thus, we are convinced that the critical role of the RAAS in COVID-19 is not completely understood, but increasing amount of data regarding the impact of SARS-CoV-2 infection on the RAAS and kallikrein-kinin system bringing more pieces to the puzzle and imply that the race for ACE has just began." (PMID 35685188, 2022). "Studies reporting increased ACE2 expression with angiotensin (Ang)-converting enzyme-1 (ACE-1) inhibitors (ACEIs) and Ang type 1 receptor (AT1R) antagonists (ARBs) suggested that renin-angiotensin system (RAS) blockers could worsen the prognosis of COVID-19 patients." (PMID 35563515, 2022). "However, the weakness of this hypothesis is the lack of evidence that ACE inhibitors and angiotensin 2 receptor blockers increase the risk of SARS-COV-2 infection or an unfavorable course of COVID-19." (PMID 33925881, 2021). "Additionally, in a retrospective multicenter study conducted in China, with 1128 hypertensive patients diagnosed with COVID-19 (188 received ACE inhibitors or ARB and 940 without receiving ACEI/ARB), the mortality rate was higher in the population that did not receive ARB/ACEI drugs (9.8% vs. 3.7%)." (PMID 33920748, 2021). "In addition, the medication classes reviewed, include anticoagulation, angiotensin converting enzyme (ACE) inhibitors, angiotensin II receptor blockers (ARB), convalescent plasma, non-steroidal anti-inflammatory drugs (NSAIDs), human recombinant soluble ACE2, and the BNT162b2 mRNA COVID-19 vaccine." (PMID 34177298, 2021). "While novel in concept, there is insufficient data on ACE/CCB combinatorial therapies available to verify whether these observations are translatable to humans, as no studies have evaluated the effects of combinations of RAS inhibitors and CCBs in COVID-19 clinical trials." (PMID 33805419, 2021). "For example, compared to calcium channel blockers (CCBs), neither angiotensin-I-converting enzyme inhibitors (ACEIs) (OR = 0.91, 95% CI: [0.67, 1.23]) nor angiotensin-II receptor blockers (ARBs) (OR = 0.90, 95% CI: [0.62, 1.33]) showed a reduction of poor COVID-19 outcomes." (PMID 34090358, 2021). "Besides, treatment with ACE inhibitors/angiotensin II receptor blockers (ARB) and high level of ACE 2 expression could result in delayed viral clearance and propensity of these individuals to COVID-19." (PMID 32851877, 2020). "In addition, when any negative effect of use of ACE inhibitors or ARBs is identified, changing medication might be an easy intervention to reduce morbidity and mortality from COVID-19." (PMID 32587077, 2020). "In addition to ACE inhibitors and statins, ET-1 antagonists and NO donors might also be considered as compounds with the potential to improve SV graft performance in CABG patients infected by COVID-19." (PMID 33118741, 2020). "In fact, recent studies in different populations and with different designs arrived at the consistent message that the continued use of ACE-inhibitors and ARBs is unlikely to be harmful in patients with COVID-19 and this may certainly reduce any fear of contagious for these patients." (PMID 33339541, 2020). "The distribution of ACE-1 (rs4343), TMPRSS2 (rs12329760) and ACE-2 (rs908004) SNP genotypes among severe, non-severe COVID-19 patients and healthy control was analyzed." (PMID 37426824, 2023). "Distribution of ACE-1 (rs4343), TMPRSS2 (rs12329760) and ACE-2 (rs908004) SNPs Genotypes among severe and non-severe COVID-19 patients." (PMID 37426824, 2023). "The frequency of the GG genotype ACE gene rs4331 and CT genotype ACE2 gene rs2074192 were dominant in both the COVID-19 and non-COVID-19 groups." (PMID 37667339, 2023).